AHRR (aryl hydrocarbon receptor repressor)
Diseases named in the same sentence as AHRR in open-access papers (continued):
Sharing a sentence is not in itself a finding about the gene and the disease.
conduct disorder (1 paper, 2018). A disorder diagnosed in childhood or adolescence age group characterized by aggressive behavior, deceitfulness, destruction of property or violation of rules that is persistent and repetitive, and within a one year period. "Despite the small size of the population studied, DNA methylation at AHRR and GFI1, but not at CYP1A1, were shown to be related to the severity of conduct disorder and ADHD in children of smoking mothers." (PMID 29618728, 2018).
dengue fever (1 paper, 2018). "For dengue fever (DF), we found evidence of significant association with CHST10, AHRR, PPP2R5E and GRIP1 genes, which participate in the xenobiotic metabolism signaling pathway." (PMID 29447178, 2018). "For the AHRR gene, the protective phenotype also has a lower expression profile, and as this protein will inhibit AHR protein, these individuals will have a higher expression of AHR, which is opposite to the expression pattern observed in the dengue patients transcriptome." (PMID 29447178, 2018).
endometriosis (1 paper, 2016). The growth of functional endometrial tissue in anatomic sites outside the uterine body. "The relevance of AHRR methylation to theory of endometrial origin of endometriosis is intriguing and worth further examination." (PMID 26759613, 2016).
gastric adenocarcinoma (1 paper, 2012). "Our results showed significantly decreased expression of AHRR in gastric cancer tissues, and confirmed the expression of AHRR as an independent risk factor for primary gastric adenocarcinoma patients." (PMID 22952704, 2012). "Kaplan-Meier survival curves and Multivariate Cox analysis revealed that decreased expression of AHRR was significantly associated with poor prognosis in gastric adenocarcinoma patients." (PMID 22952704, 2012). "Immunohistochemistry analysis indicated that AHRR expression was significantly decreased in 175 of 410 (42.7%) gastric adenocarcinoma cases." (PMID 22952704, 2012). "In the current study, we estimated the expression of AHRR in gastric adenocarcinoma by real-time PCR, western blotting and immunohistochemistry, in addition to analyzing its clinicopathological and prognostic significance in a large amount of human samples." (PMID 22952704, 2012). "In this study, the expression of AHRR in primary gastric adenocarcinoma was estimated using quantitative real-time PCR (qRT-PCR), western blotting and immunohistochemistry." (PMID 22952704, 2012). "In conclusion, the present study suggests that low AHRR expression independently predicts worse overall survival in patients with gastric adenocarcinoma." (PMID 22952704, 2012). "However, in the current study, we observed exclusively a cytoplasmic expression pattern of AHRR proteins in gastric adenocarcinoma tissues." (PMID 22952704, 2012). "Our data suggests that, in primary gastric adenocarcinoma, AHRR may play as a suppressor gene and its expression status has the potential to be an independent prognostic factor." (PMID 22952704, 2012). "Furthermore, a multivariate Cox regression analysis confirmed distant metastasis (P = 0.044) and AHRR expression (P = 0.004) as independent predictors of the overall survival of patients with gastric adenocarcinoma." (PMID 22952704, 2012). "However, to the best of our knowledge, no previous reports exist concerning the expression status of AHRR and the prognostic value of this protein in primary gastric adenocarcinoma." (PMID 22952704, 2012). "Moreover, we expect that AHRR may function as a useful target for new therapeutic interventions against gastric adenocarcinoma." (PMID 22952704, 2012). "We illustrated that AHRR was expressed at lower levels of both mRNA and protein in gastric adenocarcinoma tissues than in corresponding non-cancerous mucosa, in agreement with previous statistics shown in other types of tumor samples." (PMID 22952704, 2012). "However, to date, the prognostic significance of AHRR in gastric adenocarcinoma has not yet been evaluated." (PMID 22952704, 2012).
gastric cancer (1 paper, 2012). A primary or metastatic malignant neoplasm involving the stomach. "Cox hazard ratio regression analyses further demonstrated that the AHRR expression level was an independent risk factor for overall survival, suggesting that this value may serve as a prognostic biomarker for gastric cancer patients after surgery." (PMID 22952704, 2012). "Future studies in this field are necessary because a better understanding of AHRR function in malignancies has the potential to improve the prognosis of gastric cancer." (PMID 22952704, 2012). "A Kaplan-Meier survival analysis showed a significant correlation between low expression of AHRR and poorer clinical outcome of gastric cancer patients after radical operation." (PMID 22952704, 2012). "However, the molecular mechanisms involved in the regulation of AHRR in gastric cancer require further investigation." (PMID 22952704, 2012). "Our observations are consistent with the idea that AHRR plays as a tumor suppressor and further suggest that AHRR might play an important role in the tumor progression of gastric cancer." (PMID 22952704, 2012). "However, the functional role and mechanisms of active AHRR isoform in gastric cancer are unclear, which needs further investigation in the future research." (PMID 22952704, 2012). "Correlation between AHRR expression and clinicopathological variables of 410 gastric cancer cases." (PMID 22952704, 2012). "Additionally, we identified the relationship between AHRR expression and clinicopathological features, and we evaluated its prognostic value to post-resection survival in gastric cancer." (PMID 22952704, 2012). "However, the functional role and mechanisms of AHRR in gastric cancer are unclear, which needs further investigation in the future research." (PMID 22952704, 2012). "The AHRR protein levels in the resected gastric cancer samples were determined by western blotting." (PMID 22952704, 2012). "The mRNA levels of AHRR were estimated by qRT-PCR assays on 40 pairs of resected specimens (tumor tissue samples and matched adjacent non-tumor tissue samples) from eligible gastric cancer patients." (PMID 22952704, 2012). "The relative mRNA expression of two AHRR isoforms (with or without exon 8) was determined by qRT-PCR on 12 cases of resected specimens (tumor tissue samples and matched adjacent non-tumor tissue samples) from eligible gastric cancer patients." (PMID 22952704, 2012).
head and neck cancer (1 paper, 2023). A primary or metastatic malignant neoplasm affecting the head and neck. "Coherently with this latter evidence, in head and neck cancer, a higher expression of AhRR correlates with a higher production of VEGFD, upregulation of Akt, and subsequent tumor growth." (PMID 37511212, 2023).
Helicobacter pylori (1 paper, 2024). "have reported that Helicobacter pylori (H. pylori) infection hinders the expression of both AhR and aryl-hydrocarbon receptor repressor (AHRR) in the mucosa of the digestive tract, potentially leading to the progression of chronic inflammation and prolonged bacterial sustenance." (PMID 38680494, 2024).
hepatocellular carcinoma (1 paper, 2012). A malignant tumor that arises from hepatocytes. "Consistent with our findings, decreased AHRR expression was reported to be significantly associated with a higher grade of hepatocellular cancer." (PMID 22952704, 2012). "Specifically, using tissue microarray and immunohistochemistry, it was found that intratumoral AHRR was inversely correlated with time to recurrence and overall survival of hepatocellular carcinoma patients after resection." (PMID 22952704, 2012).
inflammatory skin disease (1 paper, 2021). Inflammatory skin disorders covers a broad category that includes many conditions ranging in severity, from mild itching to grave medical health complications These disorders are common in people of all ages and races. "This might suggest that the expression of the AhRR gene is related to inflammatory skin diseases." (PMID 34884515, 2021). "It is not yet clear whether AhRR methylation affects inflammatory skin diseases." (PMID 34884515, 2021).
lupus (1 paper, 2025). "Furthermore, the compromised gut barrier of lupus mice might be attributed to intestinal epithelial γδT loss associated with reduced AHRR expression and subsequent oxidative stress." (PMID 39871323, 2025). "Our results suggested that the loss of γδT caused by low AHRR expression may not be limited to intestinal disorders and may also contribute to extra-intestinal autoimmune diseases such as lupus." (PMID 39871323, 2025).
lymph node metastasis (1 paper, 2012). "Univariate Cox regression analyses showed that depth of tumor infiltration, local lymph node metastasis, distant metastasis, TNM stage, tumor size and AHRR expression were significantly interrelated with overall survival." (PMID 22952704, 2012).
medulloblastoma (1 paper, 2020). A malignant, invasive embryonal neoplasm arising from the cerebellum. "Determining to what extent high AHRR expression in human SHH medulloblastoma is associated with elevated TGFβ-SMAD3 signalling will be an important next step to identify patients that may benefit from TGFβ-SMAD3 inhibition and/or AHR agonist therapies." (PMID 31924815, 2020). "Transcriptomic analyses of human SHH medulloblastomas indeed identified a substantial subset of SHH primary tumours with high AHRR expression and poor prognosis in two independent patient cohorts." (PMID 31924815, 2020). "Our human transcriptomic analyses identified AHRR expression as a novel biomarker for aggressive SHH medulloblastoma in two of three independent cohorts investigated." (PMID 31924815, 2020). "Human SHH medulloblastomas with high expression of the AHR repressor (AHRR) exhibited a significantly worse prognosis compared to AHRRlow tumours in two independent patient cohorts." (PMID 31924815, 2020). "When examining the association between AHRR expression in SHH tumours and patient survival, we found a statistically significant reduction in patient survival in medulloblastomas with high (>median) AHRR expression." (PMID 31924815, 2020).
myocardial infarction (1 paper, 2022). Gross necrosis of the myocardium, as a result of interruption of the blood supply to the area, as in coronary thrombosis. "By way of comparison, DNA methylation at AHRR mediated an estimated 16% and 18% of the smoking effect on increased risk of myocardial infarction and death after myocardial infarction, respectively." (PMID 35012325, 2022). "These associations persisted both after adjustment for exposure to cigarette smoke, as proxied by AHRR DNA methylation, and after additional adjustment for other known correlates of myocardial infarction incidence." (PMID 35012325, 2022).
neuroblastoma (1 paper, 2024). Neuroblastoma (NB) is the most common solid, extracranial childhood tumor. "Using targeted transcriptomic analysis and qPCR, we observed a significant increase in the expression of genes related to the AHR pathway (CYP1A1, CYP1B1, AHRR) in mouse OPCs and human neuroblastoma SH-SY5Y cells after treatment with EDA." (PMID 38672460, 2024).
psoriasis (1 paper, 2021). An autoimmune condition characterized by red, well-delineated plaques with silvery scales that are usually on the extensor surfaces and scalp. "Although the effect of AhRR on cigarette smoke-induced DNA methylation needs to be further examined, the results of TCDD promote AhRR hypomethylation and gene expression, as well as suggesting an association between AhRR and psoriasis in HaCaT cells." (PMID 34884515, 2021). "In conclusion, the AhR agonist TCDD increases pro-inflammatory cytokines associated with psoriasis skin tissue through activation of the AhRR/NF-κB signaling pathway." (PMID 34884515, 2021). "In conclusion, we confirmed AhRR hypomethylation and increased AhRR gene expression in lesion skin from psoriasis patients, and increased expression of psoriasis-associated proinflammatory cytokines and S100 protein via AhRR-NF-kB signaling." (PMID 34884515, 2021). "In our study, hypomethylation of the AhRR gene was dominant in current smoking patients with psoriasis in the body loci of the gene." (PMID 34884515, 2021). "The AhRR gene is significantly elevated in both the epidermis and dermis of the lesional skin of patients with psoriasis." (PMID 34884515, 2021). "AhRR gene expression was significantly increased in the whole layers of the epidermis of psoriasis more than in the healthy skin group." (PMID 34884515, 2021). "The results showed that hypomethylation of the AhRR gene was dominant in current smoking patients with psoriasis in the body loci of the gene." (PMID 34884515, 2021). "On the basis of this study, we investigated the increased expression level of AhRR in patients with psoriasis to understand the role of AhRR." (PMID 34884515, 2021). "DNA methylation of AhRR was performed by Infinium Human Methylation450 BeadChip in PBMC of psoriasis patients and methylation-specific PCR (MSP) in HaCaT cells." (PMID 34884515, 2021). "We performed immunohistochemistry to investigate the localization of AhRR expression in five patients with psoriasis and five healthy controls." (PMID 34884515, 2021). "DNA methylation from peripheral blood mononuclear cells (PBMC) of psoriasis patients and PBMC of healthy volunteers exhibited hypomethylation in several loci of the AhRR gene in patients with psoriasis." (PMID 34884515, 2021). "In this study, we identified hypomethylation and overexpression of AhRR in the lesional epidermal skin of patients with psoriasis, and TCDD reacted with AhRR, AhR repressor, to confirm the effect of increasing pro-inflammatory cytokines in psoriasis skin tissues along with HaCaT cells." (PMID 34884515, 2021). "The aim of this study was to determine whether methylation and expression of AhRR plays a role in psoriasis, and to investigate the mechanism involved." (PMID 34884515, 2021). "AhRR hypomethylation in PBMC of psoriasis patients and pAhRR-HaCaT cells was confirmed." (PMID 34884515, 2021). "Our results showed that AhRR was hypomethylated and overexpressed in the lesional skin of patients with psoriasis, thereby increasing AhRR gene expression and regulating pro-inflammatory cytokines through the NF-κB signaling pathway in TCDD-treated HaCaT cells." (PMID 34884515, 2021). "We verified AhRR gene expression in the epidermis from psoriasis patients and healthy controls." (PMID 34884515, 2021). "Simultaneously, epidermal AhRR and CYP1A1 mRNA expression in psoriasis skin tissue was significantly increased compared to healthy skin tissue." (PMID 34884515, 2021). "We aimed to determine whether AhRR is hypomethylated in PBMC of psoriasis patients, as well as to examine the expression of psoriasis-related inflammatory cytokines and antimicrobial peptides after 2,3,7,8-tetrachlorodibenzo-p-dioxin (TCDD) treatment in HaCaT cells overexpressing or silencing AhRR." (PMID 34884515, 2021).
tumor (49 papers, 2010 to 2025). "Out of 273 tumours analysed, 26 (9.5%) exhibited mutations or amplifications in AHRR, while 7 (3%) displayed copy number changes (amplifications and deletions) in SFRP2." (PMID 38361045, 2024). "On the contrary, loss or downregulation of AHRR is proposed to have pro-oncogenic functions and drives tumour progression." (PMID 38361045, 2024). "The results from our study in NHL are consistent with reverse causality in which the observed differences in AHRR methylation reflect a response to tumor growth preceding clinical diagnosis." (PMID 37691855, 2023). "AHRR encodes the aryl hydrocarbon receptor repressor (AhRR), which acts as a tumor suppressor gene in multiple human cancers." (PMID 35778420, 2022). "Notably, the cg05575921 CpG site in the AHRR gene, a tumor suppressor gene, was consistently associated with smoking and an increased risk of cancer mortality." (PMID 40611182, 2025). "Specifically, we used stratified analyses by time from blood draw to diagnosis to address whether differences in AHRR methylation levels could provide a long-term marker of NHL susceptibility or instead reflect a response to tumor growth prior to diagnosis." (PMID 37691855, 2023). "Therefore, it is not unlikely that intrinsic- as well as host-dependent effects of AhRR are mediated through repression of the PKA/C/EBPβ pathway causing inhibition of tumor growth." (PMID 33763068, 2021). "However, the AHRR is a putative tumor suppressor gene encoding a competitive suppressor of the aryl hydrocarbon receptor (AHR)." (PMID 32928150, 2020). "AHRR gene has been reported to encode two isoforms and the isoform without exon 8 is the active isoform, which is the predominant form of AHRR expressed in multiple human tissues and human tumor cell lines." (PMID 22952704, 2012). "The repressor of the aryl-hydrocarbon receptor (AHRR) showed an expression profile in line with the current understanding of it as a tumour suppressor being higher expressed in primary tumours versus relapse." (PMID 38361045, 2024). "AHRR is a recognized tumor suppressor that regulates the activity of AHR, whereas NCOA2 acts as a transcriptional co-activator of nuclear hormone receptors." (PMID 39432588, 2024). "In vitro data further supported the tumour suppressor role of AHRR and the pro-tumorigenic role of SFRP2." (PMID 38361045, 2024). "AHRR expression was higher in primary tumours (p < 0.0001) and correlated with better patient survival (p < 0.05)." (PMID 38361045, 2024). "Our results show that AHRR (tumour suppressor) and SFRP2 (oncogene) are differentially expressed between primary and recurrent tumours both on the gene and the protein level and furthermore act as protein-based prognostic markers for HGSOC." (PMID 38361045, 2024). "For AHRR expression in the tumour cells, IHC data was available for 476 patients and the optimal prognostic cutoff out of 209/449 (46%) possible cutoffs was 55.16 (H-score)." (PMID 38361045, 2024). "The mRNA-based Kaplan–Meier analysis is furthermore puzzling since AHRR expression consistently indicated a tumour suppressor function in our own RNA and protein analysis in the PRI-REC cohort." (PMID 38361045, 2024). "Collectively, the data support a potential tumour-suppressive role of AHRR, in strong agreement with our clinical samples data." (PMID 38361045, 2024). "AHRR is a known tumor suppressor gene involved in the regulation of cell growth and differentiation, and detoxification pathways." (PMID 37511531, 2023). "Our results show that AHRR hypomethylation in blood leukocytes is associated with a higher risk of NHL in a time-dependent manner, suggesting that it occurs as a response to tumor development." (PMID 37691855, 2023). "Vogel and colleagues found that the growth of E0771 was inhibited by the overexpression of AhRR, and TCDD-dependent tumor promotion was inhibited by the expression of AhRR as well." (PMID 37106727, 2023).